INS (insulin)
Diseases named in the same sentence as INS in open-access papers (continued):
Sharing a sentence is not in itself a finding about the gene and the disease.
tumor (continued). "In vivo experiment showed Insulin combined with 5-FU suppressed tumor volume by 35% compared with 5-FU alone and 73% compared with control in CC xenograft mice." (PMID 34034636, 2021). "Mid- and long-term systemic injection of OCT-AAVP-TNF in transgenic mice with pancreatic insulinomas induced tumor response, as determined by the decreased insulin secretion, total choline levels, and tumor sizes." (PMID 33671476, 2021). "Since PDAC patients often have a need for replacement of insulin-producing cells, conversion of tumor cells with a ductal/exocrine origin to endocrine β cell-like cells is an attractive therapeutic option." (PMID 34771704, 2021). "ImpL2 is the fly homologue of the human insulin growth factor binding protein (IGF binding protein) and drives wasting by reducing insulin signaling in peripheral tissues of tumor-bearing adults." (PMID 34831432, 2021). "The results showed that the combination of the two inhibitors significantly suppressed the stimulated proliferation of HCT116 xenografts by insulin and OA, and the tumor shrank remarkably and tended to become smaller as time went." (PMID 34434893, 2021). "Recent studies have demonstrated that ImpL2 is a tumor-derived wasting factor, which induces a reduction in systemic insulin/IGF signaling." (PMID 34078667, 2021). "Our results have clinical implications for PDAC patients, who in addition to eradication of tumor cells have a need for replacement of insulin-producing cells." (PMID 34771704, 2021). "Since our observations indicate that Wg supports yki3S/A tumor growth by increasing insulin/IGF signaling, we decided to investigate which branch of the insulin/IGF pathway is essential for yki3S/A tumor growth." (PMID 34078667, 2021). "SIRT6 over‐expression significantly reduced myostatin expression and plasma free fatty acids levels but maintained plasma insulin levels in tumour‐bearing mice." (PMID 34212132, 2021). "Under such condition, a T2DM along with elevated, intrapancreatic, interstitial insulin concentrations would impact tumor development more severely." (PMID 34202040, 2021). "There is evidence that physical activity during treatment and follow-up can improve cachexia by reducing the tumor's adverse effects on muscle metabolism, insulin sensitivity, and levels of inflammation." (PMID 33263787, 2021). "All PanNETs examined expressed insulin in the tumor mass and a few also exhibited expression of glucagon and somatostatin." (PMID 34862365, 2021). "Our findings are in agreement with the earlier study, where Thackeray and colleagues have reported that systemic administration of low doses of insulin reduces tumour growth." (PMID 34212132, 2021). "Metformin and insulin targeted similar pathways and mostly acted on proteins related to proliferation, migration, and changes in the tumor microenvironment, especially cellular immune response." (PMID 33690729, 2021). "We identify overexpression of stearoyl-coenzyme desaturase (SCD1) as a molecular signature of HFHS tumors that largely predicts the tumor sensitivity to insulin by increasing insulin receptor (IR) expression and tumor growth." (PMID 34162829, 2021). "This is particularly driven by changes in the local tumor microenvironment, including an alternating exposure to insulin." (PMID 34202040, 2021). "The first is the insulin-dependent pathway which relies on insulin lowering function of the drug, thus decreasing proliferative capacity of the tumor." (PMID 33639681, 2021). "SH3BP4 is a potential tumor suppressor, and its methylation is related to impaired insulin signaling." (PMID 34635168, 2021). "In line with this, blood glucose levels, a reliable marker for insulin-producing tumor cell burden, was stable over the first treatment weeks, but continuously decreased in non-irradiated RIP1-Tag2 mice." (PMID 34335959, 2021). "Confirming our insulin results in the NC-fed mice, insulin increased tumor growth in HFD mice compared to mice with saline pumps." (PMID 33495474, 2021).
tumor (continued). "AMPK is not only an important regulator in cellular energy metabolism but also plays an essential role in many physiological processes such as tumor growth, inflammation, and enhanced insulin sensitivity." (PMID 34650665, 2021). "Insulin and insulin‐like growth factors (IGFs) stimulate nutrient uptake by tumor cells through the PI3K/Akt/mTOR signaling pathway to promote proliferation." (PMID 34387383, 2021). "Because of its function within the PI3K pathway, increased insulin is likely to stimulate insulin receptor (IR)-rich tumours promptly activating downstream signalling and tumour maintenance." (PMID 33810522, 2021). "Authors interpreted that by maintaining physiological level, insulin is re‐directed to other organs in the body such as heart and muscle, and therefore, tumour is deprived of glucose, which is the essential nutrient for tumour growth." (PMID 34212132, 2021). "Indirect effects include a reduction in circulating glucose and insulin levels via a blockage of gluconeogenesis in the liver, which diminishes insulin resistance due to an inhibition of the IGF1 signaling pathway in tumor cells." (PMID 33690729, 2021). "Ketogenic diets, through decreasing glucose and insulin levels, also exerted anti-tumor effect which was documented by Klement in his review." (PMID 33562380, 2021). "The excess of circulating insulin, in sarcopenic obesity, induces growth and proliferation of some cell lines, favoring the appearance of neoplasms." (PMID 33919368, 2021). "The analysis showed a significant difference (P = 0.01) in the expression of INS in the tumours compared to the normal adrenal gland." (PMID 34170845, 2021). "There is also crosstalk between IGF/insulin and estrogen receptor (ER) pathways contributing to tumor progression and endocrine resistance." (PMID 34606580, 2021). "Our ORA bioinformatic analysis provides putative tumor promoting pathways to investigate that would be acquired during chronic IL-1 exposure, such as insulin and interferon gamma signaling, glucose homeostasis and metabolism and cell adhesion." (PMID 34988553, 2021). "MCL1 mRNA and protein expression was found to be increased under insulin treatment in human granulosa-like tumor cells." (PMID 34413875, 2021). "The most frequently mentioned entities in the gene/protein and disease categories were insulin and neoplasms, respectively, which appeared in 329.4K and 2.46M PubMed records, respectively." (PMID 34322655, 2021). "Elevations in insulin were present in 57% (8 of 14, red symbols) of tumor-bearing females with 10.8-fold being the highest observed increase relative to control animals." (PMID 34862365, 2021). "As seen for the OVX model, the tumor weight correlated with fasting insulin and HOMA-IR in VCD mice." (PMID 33495474, 2021). "We did not observe a clear tumor promoting effect by insulin glargine administration, possibly indicating that endogenous mouse insulin already provided maximum tumor stimulation." (PMID 34831367, 2021). "Initially, we assessed the expression levels of circMTO1 in human granulosa-like tumor cells after insulin treatment." (PMID 34413875, 2021). "Secreted ImpL2 from epithelial tumor cells induces systemic organ wasting and insulin resistance by antagonizing insulin signaling." (PMID 33526430, 2021). "Dihydromyricetin, as a bioactive polyphenol, has been used for anti‐inflammatory, anti‐tumour and improving insulin sensitivity." (PMID 34676967, 2021). "By reducing Cxcl10 mRNA expression in muscle as well as due to downregulation of circulating CXCL10 level, SIRT6 probably helps to avoid β‐cell destruction, maintaining insulin level and thereby inhibiting tumour progression." (PMID 34212132, 2021). "Here, we aim to verify the effect of insulin and potential role on CC resistant to 5-FU and found that insulin combined with 5-FU suppressed CC tumor progression via inhibiting the phosphorylation of survivin." (PMID 34034636, 2021).
tumor (continued). "This forms an InR-SIK-Yki-Wg/InR signaling loop that potentiates glucose uptake, insulin sensitivity and secondary tumor formation." (PMID 34240146, 2021). "Overproduction of hormones (e.g. oestrogen), adipokines (e.g. leptin), and insulin that promote tumour cell survival and proliferation leads to tumour growth." (PMID 34302062, 2021). "AMPK-activated protein kinase (AMPK) is known as an energy sensor that regulates cellular metabolism by mediating the insulin pathway, and its phosphorylation is triggered by glucose stress or hypoxia in the tumor microenvironment." (PMID 33937040, 2021). "tumors produce a large number of substances with insulin activity, which can produce insulin effect, which was initially attributed to the increase in tumor size and glucose utilization." (PMID 35049191, 2021). "The data revealed that metformin and insulin targeted similar pathways in the present study and mostly acted on proteins related to proliferation, migration and tumor immune response." (PMID 33690729, 2021). "We propose that the mechanism by which vitamin D will improve tumor response is by increasing antitumor immunity and insulin response, thereby preventing inflammation-related radioresistance." (PMID 35008602, 2021). "Conversely, in IR-B overexpressing cells, insulin predominantly induced the expression of genes primarily involved in the regulation of metabolic pathways and, to a lesser extent, tumor growth and angiogenesis." (PMID 34831367, 2021). "To investigate the effect of high insulin and OA environment on tumor growth in T2D, we established the HCT116 cell xenograft model." (PMID 34434893, 2021). "The mean tumor weight in each mouse showed a positive correlation with fasting insulin levels and HOMA-IR." (PMID 33495474, 2021). "Elevating insulin using a mini-pump completely abrogated the effect of TRF on inhibiting tumor growth." (PMID 33495474, 2021). "RIF upregulated several key regulatory proteins that play a key role in tumor suppression, DNA repair, insulin signaling, glucose, and lipid metabolism, circadian clock, cytoskeletal remodeling, immune system, and cognitive function." (PMID 35372458, 2021). "A number of insulin-lowering drugs have been shown to have tumor inhibitory effects in various mouse models of cancer." (PMID 33495474, 2021). "Allografts also retained the well-differentiated neuroendocrine phenotype of the primary tumors, including tumor architecture and expression of ChA and insulin." (PMID 34862365, 2021). "The anabolic and anti-apoptotic actions of insulin promote tumor development in hyperinsulinemic subjects through binding of insulin to the insulin receptor (IR), the insulin like growth factor-insulin receptor (IGF-IR) or a hybrid receptor (IR-IGF-IR)." (PMID 34535145, 2021). "Effective inhibition of tumor growth was achieved using the INS peptide (1.25 mg/kg) that was injected, along with the CD24-targeted lentiviral particles, twice weekly for two weeks." (PMID 33958722, 2021). "GB brains with high insulin signaling in neurons also showed a reduction in the number of glial cells and in tumor volume." (PMID 33526430, 2021). "CDKN2A/B are tumor suppressors with reported roles in both cellular senescence and insulin secretion; in fact, they are related to the reduced proliferation and regeneration of beta-cells, and they reduce the secretory function of insulin." (PMID 33810109, 2021). "While the IR-B is considered the major physiological mediator of insulin-dependent metabolic actions, the IR-A plays an increasingly recognized role in fetal growth and tumor biology." (PMID 34831367, 2021). "Similar to the engineering of the MIN cell lines, the beta-tumour cell line (βTC) series was derived from tumours that were generated via transgenic mice expressing the SV40 T antigen under the control of the insulin promoter." (PMID 34940547, 2021).
tumor (continued). "Because many metabolic responses of skeletal muscle, such as glucose and fatty acid uptake, are mediated through insulin, its regulation by SIRT6 is an appealing strategy, not only to control tumour growth but also to limit muscle loss." (PMID 34212132, 2021). "Another strategy to consider is targeting of adipocyte lipolysis, perhaps by reducing inflammation within the tumor microenvironment or enhancing insulin sensitivity." (PMID 33968771, 2021). "Insulin supports tumorigenesis and reduces the transport of chemotherapeutic agents to the tumor by changing the microvasculature." (PMID 34202399, 2021). "Together, these results indicate that in 4T1/IR-A cells, insulin is considerably more effective in stimulating motility, invasion, and anchorage-independent growth, all critical hallmarks of tumor progression." (PMID 34831367, 2021). "For example, tumor burden, toxic treatment protocols, and emotional and physical stress can combine to elevate blood glucose and insulin levels thus preventing the patient from achieving therapeutic GKI values." (PMID 32219096, 2020). "The IGF‐II gene is located, adjacent to the insulin gene, on chromosome 11p15.5, a region which contains several imprinted genes, including two adjacent tumor suppressor genes, H19 and p57kip2." (PMID 32026557, 2020). "The tumor is characterized by endogenous hypersecretion of insulin and ensuing development of symptoms of neuroglycopenia and the catecholaminergic response." (PMID 32733714, 2020). "Effects of insulin on cell proliferation and tumor development have also been reported in cell culture as well as animal studies." (PMID 32133259, 2020). "A tumor xenograft model in BALB/C nude mice was used to verify insulin‐induced oxaliplatin resistance in vivo, and the results agreed with those from the in vito experiments." (PMID 32248666, 2020). "It has a wide range of biological functions, such as regulating lipid metabolism, improving insulin sensitivity, modulating anti-tumor mechanisms, and inhibiting inflammation." (PMID 33281727, 2020). "Axon guidance, focal adhesion and insulin signaling pathways were reported to affect multiple cell types connected through the tumor microenvironment and act as the major mediator of signal transduction in the metastasis and promotion of tumors." (PMID 33374139, 2020). "In our study, SFRP2 promoter methylation in tumor area was positively correlated with insulin and HOMA-IR in tumor tissue from > 30th CRC patients, but also SFRP2 methylation in tumor-free area was correlated with HOMA-IR." (PMID 32517740, 2020). "This concept is supported by studies demonstrating insulin-mediated acceleration of tumor development in humans and mouse models." (PMID 32842547, 2020). "Cell-autonomous Akt2 ablation inhibited primary tumour formation whereas germline or inducible systemic deletion of Akt2 enhanced tumour development via elevated circulating insulin levels leading to hyperactivation of AKT1." (PMID 33276499, 2020). "Reduction of systemic insulin levels in melanoma tumor-bearing mice due to consumption of large amounts of glucose by the tumor tissue interfered with cardiac glucose uptake and was associated with cardiac atrophy and dysfunction." (PMID 32542459, 2020). "Yki gut tumor-bearing flies display a systemic wasting syndrome and display elevated levels of the insulin antagonist ImpL2, in addition to canonical Yki targets that include Sd, the DNA-binding partner of Yki." (PMID 32540914, 2020). "This maneuver resulted in a decrease of [Ca2+]c as expected from numerous observations with murine β-cells and insulin-secreting tumor cell lines as well as the restricted number of studies with human β-cells." (PMID 33193079, 2020).
tumor (continued). "This transcription factor is upregulated during various organ development and cellular events such as differentiation of Th cells in the thymus and insulin secretion in the pancreas, while it is aberrantly expressed in tumor development." (PMID 32393810, 2020). "Nevertheless, several interventions elevate the penetrance of proximal tumor formation at the permissive temperature, including reduced insulin signaling or the ablation of distal-most sheath cells." (PMID 33077477, 2020). "The promoter methylation of SFRP2 was also positively correlated in adjacent tumor-free area with insulin." (PMID 32517740, 2020). "A further experiment was performed to evaluate the secretion of insulin in response to glucose from the islets of 13-wk-old control and transgenic mice, which are characterized by late tumor development." (PMID 31903128, 2020). "Nonetheless, the insulin/IGF signaling is a key driver in tumor-stromal interactions, metastasis and PDAC progression." (PMID 32660466, 2020). "Several previous studies have explored the effect of treatment with supra-pharmacological doses of HI and insulin analogues in various tumour models in vivo." (PMID 32350367, 2020). "Decreased insulin sensitivity was also confirmed in several animal models of cachexia, such as C26 tumor-bearing mice and Walker 256 tumor-bearing rats but also in drosophila." (PMID 33202621, 2020). "The tumor-stimulating properties of insulin (INS) in BC are secondary to the fact that insulin stimulates NHE1, raising pHi and increasing glycolysis." (PMID 33050492, 2020). "These include targeting adipose tissue inflammation, reducing circulating insulin levels through dietary, pharmacological or surgical means, and decreasing circulating and tumor cell lipid synthesis, uptake and metabolism." (PMID 33604295, 2020). "Aspirin has been found to inhibit tumor growth in obese mice through lowered plasma glucose, insulin, leptin, WBC, neutrophils, lymphocytes, soluble P-selectin, TGF-β1, and glutamine." (PMID 32121098, 2020). "Aspirin mitigated tumor growth in obese mice with lowered glucose, insulin, leptin, leukocyte number, glutamine, TGF-β1, and platelet activation." (PMID 32121098, 2020). "In conclusion, IX10, which traditionally is considered a “super-mitogenic” insulin analogue, significantly increased growth of L6hIR xenograft tumours in vivo compared to HI." (PMID 32350367, 2020). "Tumor-bearing mice showed substantially decreased plasma levels of amylin, which is co-secreted with insulin by pancreatic β-cells." (PMID 32824846, 2020). "Similar to that in the mouse model, immunopanning enriched tumor OPCs were the main fraction to grow in insulin‐free minimal media regardless the growth factor provided." (PMID 33173731, 2020). "Recent comprehensive genomic analyses showed that over 90% of ECs have genomic alterations in this pathway, resulting in enhanced insulin signaling and production of optimal tumor microenvironments (TMEs)." (PMID 32842547, 2020). "Accordingly, FAM13A has been involved in multiple biological processes such as epithelial cell regeneration, tumor cell proliferation and survival, and insulin signaling." (PMID 32053709, 2020). "This association may be because a high insulin concentration increases the concentration of insulin-like growth factor 1, which, in turn, can upregulate vascular endothelial growth factor secretion and induce tumor angiogenesis, leading to tumorigenesis and metastasis." (PMID 32313131, 2020). "The evidence suggests that insulin stimulates tumor growth by decreasing the production of insulin-like growth factor-binding protein 1 (IGFBP-1), increasing the tissue bioavailability of Insuline-like growth factor (IGF)-I, or inhibiting apoptosis." (PMID 32340309, 2020).